KRAS (KRas proto-oncogene, GTPase)
Diseases named in the same sentence as KRAS in open-access papers (continued):
Sharing a sentence is not in itself a finding about the gene and the disease.
cancer (continued). "However, this can be explored in larger cohorts, as there is also increasing evidence among other types of KRAS-mutant cancer that metformin can influence survival and its efficacy needs further clinical trials in order to find a place in the treatment continuum of mCRC." (PMID 37761297, 2023). "Indeed, KRAS-driven cancer has evolved autophagy as an interception mechanism to keep ROS in check." (PMID 36765038, 2023). "Thus, KRAS mutations appear to cause the overexpression of MYC and ARF6 proteins in cancer cells." (PMID 37158894, 2023). "We previously reported the discovery of a bispecific antibody, termed V2, which can specifically bind to the KRASG12V-HLA-A*03:01 neoantigen and drive T-cell-mediated killing of KRASG12V-containing cancer cells without non-specific activity against wild-type KRAS or other codon 12 mutations." (PMID 37604828, 2023). "Furthermore, GSEA also revealed the hallmarks of malignant tumors, including inflammatory response, interferon gamma response, epithelial-mesenchymal transition, angiogenesis, focal adhesion and KRAS signaling, were significantly enriched in LGGs with higher risk score." (PMID 37488496, 2023). "Thus, our work demonstrates that co-targeting of UHRF1 and KRAS may constitute a viable therapeutic approach for KRAS mutant cancers." (PMID 37407562, 2023). "Nevertheless, this study provides a preliminary concept for understanding that alteration in oncogene KRAS expression may regulate the expression of immune checkpoint molecules, which has a direct role in the initiation and maintenance of cancer gene-driven tumorigenesis." (PMID 36902476, 2023). "Accordingly, the HMH genomic DNA mixture was determined to carry 24.1% KRAS c.35G > T, 10.1% BRAF c.1391G > T, and 24.1% BRAF c.1799T > A. The values are consistent with the theoretical value calculated from the gene mutation genotypes of the three cancer cell lines." (PMID 37686219, 2023). "Therefore, we hypothesize that treatment with DNMT1 inhibitors may constitute an alternative to UHRF1 targeting and may be a potential therapeutic approach for treatment of KRAS-driven cancer." (PMID 37407562, 2023). "In the pan-cancer analysis, a decreased probability of overall survival (OS) and disease-specific survival (DSS) was found in amplified tumors in comparison with non-amplified ones, with EGFR, CDK4, MDM2, KRAS, and CCNE1-amplified tumors being those associated with a worse prognosis." (PMID 36980521, 2023). "Two other pathways that are significantly upregulated in UM with low MITF are KRAS_SIGNALING_UP and MTORC1_SIGNALING: these are not pathways that are commonly associated with UM but both play a role in other types of cancer and specifically in metabolic reprogramming." (PMID 37240204, 2023). "Cancer genome analysis using next-generation sequencing (NGS) technologies involves sequencing and analyzing the DNA of cancer cells to identify genetic mutations known as hot-spot regions (such as KRAS and PIK3CA) that are associated with the development and progression of cancer." (PMID 37598236, 2023). "Activation of these pathways may sustain cancer growth even without gain-of-function mutations, and their activation has been shown to reduce the response to KRAS inhibition." (PMID 37925476, 2023). "Thus, lysosomes could serve as a therapeutic target in the treatment of KRAS-mutant cancers and CSCs." (PMID 37402770, 2023). "Cells with a low KRAS4A/KRAS4B ratio have shown higher sensitivity to cancer treatment drugs and an association with high KRAS signaling and a poor patient outcome, suggesting that they could serve as biomarkers of sensitivity to existing cancer treatments." (PMID 37875914, 2023).
cancer (continued). "Furthermore, if a positive response is seen, whether patients will later develop therapeutic resistance to these drugs, as has been shown for both MEKi and BRAF inhibitors, and perhaps now KRAS-specific inhibitors in cancer, is also unknown." (PMID 38001877, 2023). "From a translational perspective, the link between KRAS mutations and innate immune evasion suggests that targeting the KRAS/CD47 axis might compromise the ability of cancer cells to evade innate immune surveillance and increase their susceptibility to macrophage phagocytosis." (PMID 36413402, 2023). "Moreover, in some cancers of the BM2 sub-type the presence of PIK3CA mutations is not sufficient to activate the KRAS/AKT and mTOR/protein translation pathways." (PMID 36079062, 2022). "The macropinocytosis flux of KRAS mutant cancer cells may be underestimated since induction macropinocytosis of oncogenic RAS protein was found to last for more than 15 hours, while endogenously expressed mutant proteins are expected to induce persistent macropinocytosis." (PMID 35154489, 2022). "In addition, the proliferative capacity of cancer cell lines with oncogenic KRAS was less affected than that of normal cells when challenged with soft matrix growth conditions, suggesting that oncogenic RAS can promote adaptation to biomechanical stress by modulating cell stiffness." (PMID 35147163, 2022). "Here, we found that the KRAS-G12D mutation rewires amino acid metabolism, so our findings support the notion that activation of RAS mutants is a double-edged sword: it can promote cell proliferation, but it can also induce metabolic vulnerabilities during cancer progression." (PMID 35243242, 2022). "Thus, exploiting the metabolic reprogramming that takes place in KRas-driven cancers may permit the targeting of KRas, which has been difficult to target directly." (PMID 36269753, 2022). "Additional studies using mutant KRAS pancreatic and colorectal cells, as well as additional analyses using corresponding TCGA RNA-seq data, would be needed to determine the broader physiological relevance of our findings across other cancer types driven by oncogenic RAS signaling." (PMID 35858545, 2022). "The expression of microRNAs (miRNAs) and the KRAS oncogene are known to be dysregulated in various cancers, while long noncoding RNAs (lncRNAs) can act as regulators of the miRNAs targeting KRAS oncogene in different cancers and have gradually become a focus of research in recent years." (PMID 34489556, 2022). "Therefore, inhibition of PDEδ can be an effective path for KRAS-induced cancer treatment." (PMID 35409064, 2022). "In addition, this analysis revealed the presence of several differentially expressed transcripts encoding key components of signal transduction cascades frequently found deregulated in several human cancers, including mTOR, KRAS, and TNF-α/NF-kB signaling pathways." (PMID 35918402, 2022). "The formation of non-canonical G-quadruplex (G4) DNA structures within KRAS’s core promoter offers a molecular target to decrease gene expression, utilizing a small molecule with promise in cancer cells that harbor aberrant KRAS signaling and in a manner independent of the mutational status." (PMID 36011352, 2022).
cancer (continued). "Therefore, a drug delivery strategy may be desired to selectively deliver these compounds into PDAC cancer cells, which are generally KRAS mutant, and avoid collateral damage to unwanted cellular components, such as lymphocytes in the TME." (PMID 35154474, 2022). "RAF1 could be an essential target to block KRAS mutant cancers." (PMID 36330448, 2022). "Therefore, activated KRAS controls various cellular processes, including survival, growth, proliferation, differentiation, and apoptosis, all of which are known as hallmarks of cancer." (PMID 34489556, 2022). "In addition to Kras, Ccl2, and Il1b, a battery of other transcripts originated within the signature of KRAS-mutant cancers derived from the transcriptomes of our cell lines, providing synthetic lethality candidates for in vivo KRAS dependency for future research." (PMID 35327394, 2022). "Moreover, berberine and coptisine significantly lowered the KRAS mRNA levels in cancer cells." (PMID 36224201, 2022). "This means that VC alone, even at a high dose, is effective in inducing a potent oxidative stress in KRAS-mutant cancer cells and reaching a potent cytotoxic impact in clinical settings that might not be feasible consistently because of DHA’s competition with glucose." (PMID 36359850, 2022). "In addition, FRA1 contributed to oncogenic KRAS-driven PD-L1 expression in high risk, premalignant human bronchial epithelial cells, suggesting that FRA1 may promote cancer progression by facilitating immune evasion." (PMID 34973117, 2022). "Moreover, the findings support that IL-1β blockade might be suitable for therapy for KRAS-mutant cancers." (PMID 35327394, 2022). "The Kirsten rat sarcoma viral oncogene homolog (KRAS) gene belongs to the rat sarcoma (RAS) family of oncogenes that also includes Harvey rat sarcoma (HRAS) and neuroblastoma rat sarcoma (NRAS) viral oncogene homologs and, when mutated, can initiate or promote cancer growth." (PMID 36494601, 2022). "SHP2 activation was important resistance mechanism for blockade of MEK in KRAS-mutant cancer, and there were synergy effects between SHP2 and MEK inhibitions in PDOs of PDAC, indicating that the dual SHP2/MEK inhibitors may be applied to the treatment for KRAS-mutant PDAC patients." (PMID 36207749, 2022). "By using the similar approach, inhibition of MAPK7, an essential MEK gene, attenuated the re-activation of MAPK signaling following long-term MEK inhibition in KRAS mutant cancer cells, suggesting that targeting MAPK7 may attenuate acquired resistance to MEK inhibition." (PMID 35372044, 2022). "Consequently, distinct properties of KRAS mutant cancer cells compared to normal cells in these processes could also act in synergy with enhanced macropinocytosis in the pursuit of an ultimate goal for KRAS-targeted drug delivery." (PMID 35154489, 2022). "Interestingly, JNK inhibitor co-treatment could enhance the cancer cytotoxic effect of the ferroptosis inducers in NRAS and KRAS mutation-harboring cells (HT-1080 and MIA PaCa-2)." (PMID 36232313, 2022). "Furthermore, a recent study has also reported the elevated expression of ISM1 in the CRC tissue of patients, and on top of that, a positive correlation of ISM1 with cancer-associated signalling pathways including EMT, hypoxia, KRAS, Notch, and Hedgehog were observed." (PMID 36611811, 2022). "Whether the KRAS antibody will be effective in cancer patients needs to be explored." (PMID 35966590, 2022). "The protein-encoding KRAS is a GTPase protein, which in cancerous cells is activated to a GTP-bound activation state by cellular transmembrane receptor signaling such as EGFR, which further activates various cancer growth and proliferation pathways such as downstream MAPK and AKT." (PMID 36358856, 2022).
cancer (continued). "In KRASG12C mutant cancers, the amount of GTP-bound KRAS proteins determines the sensitivity to KRASG12C inhibitors, which interacts with and blocks KRASG12C when it is in the inactive GDP-bound state, so an increased ratio of KRAS-GTP versus KRAS-GDP cause resistance to KRASG12C inhibitors." (PMID 36483040, 2022). "Therefore, this study reinforces the hypothesis that the altered Del allele may act on the loss of miRNA548 function in patients with GC and consequently reverse the effects of KRAS silencing, which stimulates cell growth and the metastatic process of cancer." (PMID 36672804, 2022). "Furthermore, another study has also reported the elevated expression of ISM1 in the CRC tissue of patients, and on the top of that, the positive correlation of ISM1 with cancer-associated signalling pathways including EMT, hypoxia, KRAS, Notch, and Hedgehog was observed." (PMID 36611811, 2022). "More so, our study opens a new window of opportunity to improve responses to KRAS inhibition by understanding whether and how the cancer cell-educated fibroblasts contribute to support tolerance and resistance to KRAS inhibition and how we can therapeutically explore this potential vulnerability." (PMID 36010567, 2022). "Importantly, by depending on the mutant cysteine residue for binding, the compounds specifically target the KRASG12C mutant protein while sparing KRAS wild-type protein, an observation supported by the selectively inhibition of growth of cancer cell lines expressing KRASG12C." (PMID 35045886, 2022). "Exosomal KRAS mutations are present in the early stages of PDAC, as well as during its advanced metastatic stage, indicating that circulating mutations in EVs could be used to develop early cancer diagnostic tools." (PMID 35501802, 2022). "Furthermore, in KRAS mutant cancers, immune checkpoint molecules are downregulated." (PMID 36612217, 2022). "Furthermore, this also suggests that combining selinexor with a KRAS G12C inhibitor sotorasib may have synergistic efficacy in patients with cancer that have developed resistance to therapy with sotorasib (or other KRAS G12C inhibitors)." (PMID 35573474, 2022). "In PDAC tissues, PTX3 was previously found expressed by mesenchymal stellate cells in the stroma; however, in our study, PTX3 was overexpressed in cultured KRAS-transduced epithelial pancreatic cells, demonstrating that cancer cells may also produce PTX3 upon KRAS transformation." (PMID 35681634, 2022). "Thus, ARS-1620 provided the first in vivo evidence that the S-IIP targeted approach may be a promising therapeutic strategy for patients with KRAS p.G12C mutant cancers." (PMID 35045886, 2022). "Therefore, inhibition of KRAS activation is a popular and efficient method for cancer treatment." (PMID 35614051, 2022). "However, multiple RAS proteins were detected in Hs746T cells, of which only one was successfully suppressed by shKRAS induction, suggesting additional members of the RAS gene family may play a role in these cancers besides KRAS." (PMID 35326531, 2022). "Moreover, KRAS signaling plays a cancer-promoting role in multiple cancers." (PMID 36419844, 2022). "Although the exact reasons for the apparent tissue specificity of the different RAS oncogenes remain obscure, these observations suggest that KRAS is the functionally dominant RAS gene in many tissues and might explain why it is the most frequently mutated in human cancers." (PMID 35234863, 2022). "In contrast to these findings, in a case series study, Amemiya showed that KRAS mutations may be a late event in the malignant transformation to cancer, since they have been observed only in cancer but not in AE or TE." (PMID 35457244, 2022).
cancer (continued). "While the association of KRAS mutations with poor prognosis may not be unique to SHCs, the occurrence of KRAS mutation may induce sarcomatoid phenotype and indicate poor prognosis in cancers with sarcomatoid component." (PMID 36741696, 2022). "If successful, these KRAS mutation-selective inhibitors and pan-KRAS inhibitors and degraders will move beyond selective inhibitors of KRASG12C and provide novel therapeutics for not only PDAC patients but also all other patients with KRAS-driven cancers such as NSCLCs and CRCs." (PMID 36231030, 2022). "KRAS could serve as a key prognostic factor in different cancer types." (PMID 35563733, 2022). "However, in cancer cells expressing oncogenic forms of KRAS, the balance between the phosphorylation-dephosphorylation states of MYC is shifted toward an increased phosphorylation at Ser 62, thus reducing the amount MYC that undergoes ubiquitination and degradation." (PMID 36581205, 2022). "Furthermore, KRAS mutations are associated with poor prognosis in several cancers, and there is still a lack of effective targeted therapeutics designed to counteract the effects of this mutation." (PMID 34804112, 2021). "The second group belongs to nonhypermutated tumors (~84%) that are microsatellite stable (MSS) cancers with a high frequency of DNA somatic copy number alterations (SCNAs) and dysregulated Wnt pathway with frequent mutations in genes including adenomatous polyposis coli (APC) and Kirsten ras (KRAS)." (PMID 33917100, 2021). "Moreover, another metabolic advantage promoted by KRAS is the synthesis of monomeric constituents essential for cancer cell proliferation, namely amino acids, and nucleic acids, by deviating glucose toward anabolic pathways, including the pentose phosphate pathway." (PMID 34885243, 2021). "Notably, the most commonly used human TNBC cell line to study metastatic breast cancer, MBA-MDA-231, carries mutations in KRAS, BRAF, and NF1, underscoring the universality of an increase in RAS signaling strength during the progression of diverse cancer types." (PMID 34491463, 2021). "Corresponding to our biological system analysis, we propose that a combined addition of pharmacologic ascorbate and chloroquine in KRAS mutant cancer cells, with the inhibition of GLUT1 and downregulation of autophagy, might be a therapeutic approach in anti-cancer therapies." (PMID 33925206, 2021). "Therefore, the combination of MAPK and PI3K inhibitors may be a compelling regimen for the treatment of KRAS-mutant cancers." (PMID 34742312, 2021). "Moreover, KRAS exhibited more RNA alterations rather than DNA mutations in the context of various cancer types (not all)." (PMID 34245122, 2021). "However, most monotherapies targeting PI3K, AKT, and/or mTOR are ineffective in KRAS-mutant cancer." (PMID 34742312, 2021). "Our understanding of the role of synonymous variants in cancer is rapidly expanding, with recent studies demonstrating that they may act as drivers of the disease, altering the function of oncogenes such as RET and KRAS." (PMID 33822938, 2021).